MMP2 (matrix metallopeptidase 2)
Diseases named in the same sentence as MMP2 in open-access papers (continued):
Sharing a sentence is not in itself a finding about the gene and the disease.
cancer (continued). "For instance, neural and cancer-derived nerve growth factor (NGF), binding to its receptor TrkA expressed on cancer cells, leads to p44/42 MAPK-mediated MMP-2 overexpression in pancreatic cancer." (PMID 39906323, 2024). "The impact of PLE0 on the activity and expression levels of MMP-2 and MMP-9, two major MMPs that mediate ECM degradation, were investigated as the activity of MMP is critical in cancer metastasis." (PMID 38732748, 2024). "The interaction between matrix metalloproteinases (such as MMP-2 and MMP-9) and VEGF is a key focus in cancer research, given their combined impact on cancer progression and metastasis." (PMID 38374934, 2024). "The small size of these molecules enables them to penetrate tissues and reach intracellular targets efficiently and via inhibiting MMP-2 and MMP-9, these small molecules prevent the breakdown of the ECM, thereby limiting cancer cell invasion and metastasis." (PMID 39858430, 2024). "MMPs, especially MMP-2 and MMP-9, play essential roles in cancer metastasis by degrading key components of the ECM, thereby creating pathways for cancer cells to invade and metastasize." (PMID 39062544, 2024). "In this study, molecular docking techniques were utilized to explore the binding interactions between silymarin and two significant matrix metalloproteinases (MMPs), MMP-2 and MMP-9, which are integral to cancer metastasis." (PMID 39431222, 2024). "Metastatic CRC cells release proteolytic enzymes like matrix metalloproteinase 2 (MMP-2) and matrix metalloproteinase 9 (MMP-9) to digest the extracellular matrix (ECM), facilitating irregular cancer cords to penetrate adjacent tissues." (PMID 38468952, 2024). "A significant increase in CDH1 as well as significant decreases in CDH2 and MMP2 gene expression und s-μg indicated an induction of a mesenchymal–epithelial transition (MET) phenotype in the A549 cells, suppressing cancer progression." (PMID 38255998, 2024). "Among all of these, MMP2, MMP9, FN1, CD44, SERPINE1, and CAV1 are the most famous collaborators with PLAUR in the cell migration of multiple cancer types." (PMID 38396677, 2024). "This function is complementary to the enzymatic remodelling of type IV basement membrane collagen by MMP‐2 and MMP‐9, two zinc‐dependent endopeptidases, which thereby are involved in promoting cancer metastasis." (PMID 37581480, 2023). "CAF-derived factors, such as matrix metalloproteinase 2 (MMP2), the chemokine CXCL12, TGF-β, and IL-6, facilitate the proliferation and invasion of cancer cells in various tumors." (PMID 37174001, 2023). "DNS treatment upregulated Bcl-2 expression while downregulating Bax, MMP-2, MMP-9, mTOR, and Akt levels in cancer cells." (PMID 38192621, 2023). "Studies have reported the benefit of retinoids in preventing cancer invasion and metastasis by targeting proteases (MMP-1, MMP-2, MMP3, uPA) involved in the degradation of the extracellular matrix (ECM)." (PMID 38249515, 2023). "In this work, we show that treatment with resistin induces an increase in FAK phosphorylation levels and an increase in MMP-2 and MMP-9 secretion in PC3 cancer cells." (PMID 38137922, 2023). "MMPs, especially MMP-2 and MMP-9, have been shown to be involved in cancer cell migration and invasion." (PMID 36969058, 2023). "MMP-2 and MMP-9 play a key role in cancer progression and metastasis by degrading ECM thus, they are important predictive factors for various cancers." (PMID 38069361, 2023). "Gelatinase A (MMP-2) is an enzyme that degrades IV type collagen, a component of the basement membrane that is destroyed during cancer invasion." (PMID 36982551, 2023).
cancer (continued). "We found that a number of signaling networks and their components such as PI3K/Akt/mTOR, MMP‐2 and 9, Wnt/‐catenin, PARP, MAPK, NF‐κB, Caspase‐3/8/9, Bax, Bcl2, Smad4, Notch1, STAT3, Nrf2, and ROS signaling can be regulated in cancer cells by phytochemicals." (PMID 37132286, 2023). "MMP-14 has a central role among the MMPs and acts in cancer metastasis by degrading the ECM, increasing the secretion of pro-MMP2, pro-MMP9 and pro-MMP13, while cleaving membrane-anchored growth factors and cytokines." (PMID 36656313, 2023). "In many types of cancer, the downregulation of RECK gene expression related to the expression and the activity of MMPs, such as MMP-2 and MMP-9, has been demonstrated." (PMID 38139236, 2023). "Recent studies indicated that Snail can mediate the upregulation of several gene expressions of MMPs in cancers such as MMP-2, MMP-9, and MMP-14, and these proteases were reported to be promoters and mediators of EMT processes in cancers." (PMID 36766694, 2023). "HSPB1 stimulated the activity of matrix metalloproteinase 2 (MMP-2) through the TGF-β pathway, driving the migration of cancer cells from the prostate gland which is the prerequisite of distant metastasis." (PMID 37010714, 2023). "Bioactive assays on four cancer cell lines, A549, MCF-7, Hela, and HepG2 cells, were conducted, revealing a potential antagonistic effect on MMP-2." (PMID 37513440, 2023). "Previous studies have collectively suggested ALA as a potent inhibitor of MMP-2 and MMP-9 activities, which reduces the invasion of various cancer cells." (PMID 37496822, 2023). "Among the 23 members of the MMP family, MMP-2, MMP7, and MMP-9 are regarded as key factors involved in cancer metastasis." (PMID 37427379, 2023). "MMP-2 and MMP-9 are the major enzymes involved in the degradation of extracellular matrix (ECM) and plays crucial role in the metastatic dissemination of cancer cells." (PMID 37370134, 2023). "Previous studies have shown that CD147 positively correlates with the expression of MMP-2 and MMP-9 in both cancers, suggesting that patients with elevated concentrations of CD147 have a poorer prognosis." (PMID 36982551, 2023). "In the process of cancer angiogenesis, curcumin inhibits the growth factor VEGF and ensures stability of the extracellular matrix, which downregulates MMP-2 and MMP-9 and upregulates metalloproteinase-1." (PMID 37513855, 2023). "Overall, the effect of dandelion, or its combination with ATRA, on the expressions of MMP-2 and MMP-9 in MDA-MB231 and MCF-7 cells should be considered a novel finding that can be used in cancer treatment strategies by conducting further research." (PMID 37700002, 2023). "Matrix metalloproteinase-2 (MMP2) and matrix metalloproteinase-9 (MMP9) are matrix metalloproteases involved in cancer progression and invasion, and their expression is considered a marker of cell invasiveness." (PMID 37686467, 2023). "Similar types of MMPs were found to be increased in both cancers, namely, MMP-1, MMP-2, MMP-9, and MMP-11." (PMID 36982551, 2023). "Much evidence has been reported about several matrix metalloproteinases (MMPs) of cancer, such as MMP2 and MMP9, driving cancer invasion by degrading extracellular matrices." (PMID 37367670, 2023). "MMP2 and MMP9 have been demonstrated to play critical roles in the degradation of basement membrane collagen, as well as cancer progression and metastasis." (PMID 35871358, 2023). "Studies have also showed that overexpression of MMP-2 (gelatinase A) and MT1-MMP (collagenase) by HPV16 E6/E7 facilitates ECM degradation and cancer invasiveness." (PMID 36905477, 2023). "Pan-cancer analysis showed that MM9 was almost always downregulated among the 16 tumors, including GC; MMP2 was upregulated in BLCA, CESC, KICH, and UCEC and downregulated in CHOL, GBM, HNSC, KIRP, PRAD, SKCM, and GC." (PMID 37565919, 2023).
cancer (continued). "MMPs, especially MMP-2 and MMP-9, are usually over-expressed in a wide range of human cancer types, including OS, providing a potential therapeutic target." (PMID 37686148, 2023). "Isoliquiritigenin (25–50 μM) treatment inhibited signaling molecules such as NF‐κB, P13K/Akt, and p38, decreasing MMP‐2, MMP‐9, VEGF, and HIF‐1α expressions leading to reduce the motility of MDA‐MB‐231 cancer cells." (PMID 37132286, 2023). "The underlying mechanism revealed that SPON2 activated the nuclear factor-κB (NF-κB) signaling pathway, leading to the upregulation of matrix metalloproteinase 2 (MMP2) and MMP9, both known to promote cancer cell migration and invasion." (PMID 38260135, 2023). "The proteolytic breakdown of the extracellular matrix components by gelatinases, such as matrix metalloproteinase MMP-2 and MMP-9, is a critical step in cancer development and metastasis." (PMID 37496822, 2023). "In NSCLC cells, carbon ion (12C) radiotherapy combined with PARP-1 inhibitor significantly inhibited NF-kB expression, which followed by reduced MMP-2/9 expressions and significantly suppressed EMT and cancer metastasis." (PMID 37766868, 2023). "Fisetin exhibits its antiangiogenic role by regulating a number of important angiogenesis-related factors in cancer cells, such as VEGF, MMP2/9, eNOS, wingless and Wnt-signaling." (PMID 37626424, 2023). "MMPs, especially MMP2, promote proteolytic matrix degradation and contribute to EMT progression to favor cancer cell invasion." (PMID 36835419, 2023). "Among this family, gelatinases MMP-2 and MMP-9 can promote cancer metastasis by degrading collagen IV and gelatin, alone or in cooperation with other MMPs." (PMID 36765917, 2023). "As documented in many researches, both MMP‐2 and MMP‐9 proteins are abundantly expressed in different malignancies and these proteins facilitate cancer metastasis." (PMID 38012058, 2023). "Lastly, in CRC, elevated levels of MMP-2, MMP-9, and MMP-13 were observed in plasma and cancer biopsy samples." (PMID 38288108, 2023). "In endometrial carcinoma, CAFs promote cancer progression via the SDF-1α/CXCR4 axis, through PI3K/AKT and MAPK/ERK signaling in a paracrine-dependent manner, and increase MMP-2 and MMP-9 secretion in an autocrine-dependent manner." (PMID 37046676, 2023). "In summary, HOXA13 plays a role as a cancer-promoting gene in NPC and can promote the proliferation, migration, and invasion of NPC HNE1 cells by upregulating Snail and MMP-2." (PMID 37563232, 2023). "Matrix metalloproteinase-2 (MMP-2) is activated when HSP90, which is produced by invasive cancer cells via exosomes, is present." (PMID 37273315, 2023). "MMP-2 and MMP-9 are upregulated in most cancers and play crucial roles in modulating invasion and metastasis." (PMID 37833873, 2023). "The center and lowest energy for experimentally verified anticancer peptides (ACPs) of cancer cells in GP63, and expected standard peptides of GP63/MMP2 were between –545 and –1025." (PMID 36700237, 2023). "Those MMPs, especially MMP-2 and MMP-9, are driving forces for cancer cell invasion and metastases formation." (PMID 35600975, 2023). "Consequently, protein expression levels of PI3K, AKT, MMP2, and MMP9 that are the proteins implicated in cancer progression in the siRNA-treated group were significantly decreased, stipulating that the cancer-promoting effect of MLLT11 might be related to the PI3K/AKT signaling pathway." (PMID 38075552, 2023). "The study's findings highlight the regulation of Src activation by MMP‐2 and its interaction with the endogenous Src inhibitor CHK/MATK, which presents new possibilities for targeted cancer therapies." (PMID 38064181, 2023). "MMPs secreted by SCs, especially MMP2 and MMP9, enhance the degradation of ECM and provide loose channels for the movement of cancer cells." (PMID 36900158, 2023).
cancer (continued). "MMP-2 and MMP-9 are gelatinases involved in the invasion and metastasis of cancer cells, and their synthesis and secretion are regulated by pathways such as MAPK and FAK/Src." (PMID 38137922, 2023). "Among the factors involved in PNI, matrix metalloproteinases (MMPs), especially MMP‐2 and MMP‐9, are believed to be essential for collagen degradation and drive cancer cells to disseminate along nerves." (PMID 37830980, 2023). "All of this contrasted with the observations in other cancers such as colon (for LAMP-2) or breast (for AGTR1), which presented an increase in expression levels and consequently a decrease in MMP-2 levels." (PMID 36765855, 2023). "Many MMP members such as MMP-1, MMP-2, and MMP-9 are overexpressed in cancer and contribute to cancer cell growth, apoptosis, angiogenesis, invasion and metastasis." (PMID 37055381, 2023). "It is believed that vitamin A is related to the production and activity of MMP-2 and MMP-9 in cancer progression, metastasis, and other human diseases." (PMID 38069361, 2023). "Then, activated c-Jun increases matrix metalloproteinase 2 (MMP2) transcription, which induces cancer cell invasion and metastasis." (PMID 36831352, 2023). "As IL-17 promotes cancer cell metastasis by upregulating invasive proteins, we investigated the effect of notopterol on the expression of uPA, MT1-MMP, and MMP-2." (PMID 37894738, 2023). "Those cells are exploited by the cancer cells to further release MMP-2 and MMP-9 to degrade the surrounding extracellular matrix (ECM) that cancer cells can reach vasculature." (PMID 35600975, 2023). "MMPs (MMP-2, MMP-9, MMP-14) are able to damage the capillary layer and at the same time promote the exosmosis of cancer cells." (PMID 37895400, 2023). "Both MMP2 and MMP9 are capable of regulating migration and invasion and serve as important prognostic factors of many cancers." (PMID 37307404, 2023). "It was reported that phytochemicals have significant anti‐metastatic and anti‐angiogenesis effects by inhibiting MMP‐9 and MMP‐2 and suppressing VEGFR‐2 expression, thereby inhibiting the growth and invasiveness and adhesion of cancer cells." (PMID 37132286, 2023). "The significant link between increased angiostatin and the upregulation of MMP-2 and MMP-9, suggests possible involvement in cancer initiation, progression, and invasion." (PMID 37798646, 2023). "MiR-29a also plays a significant role in promoting apoptosis via several effectors including MCL-1, KDM5B, QKI-6, MMP2, and TNFR1 in various cancers." (PMID 37684602, 2023). "Several studies have shown that the anti-cancer properties of numerous SFB species are strongly correlated with their capacity to inhibit MMPs, notably the expression of MMP-2 and MMP-9." (PMID 37175435, 2023). "The low ability of ABCC6-silenced cells to invade the Matrigel was most likely due to the reduced expression and secretion of active forms of the two metalloproteinases MMP2 and MMP9, whose activities have been correlated with the invasive stage of carcinomas." (PMID 38003580, 2023). "As EMT is a common process that has been postulated to be responsible for carcinoma cell metastasis, the effect of the BCSC secretome on the expression of epithelial markers (CDH1, TJP1 and OCLN) and mesenchymal markers (Snail, FN1, MMP2 and VIM) was assessed." (PMID 36915147, 2023). "Another mechanism of action for the anti-cancer activity of PCA follows the downregulation of the Ras/Akt/NF-kB pathway by targeting activation of RhoB, further leading to a drop in MMP-2-mediated cellular actions in cancer cells." (PMID 36247004, 2022). "Matrix metalloproteinase-2 (MMP-2), MMP-9, and urokinase-PA (u-PA) are enzymes that degrade extracellular matrix components and play a key role in cancer invasion and metastasis." (PMID 35449807, 2022).
cancer (continued). "Our results showed that the expression of MMP2 and MMP9 was reduced with Rab31 knockdown, decreasing the capability of cancer cells to metastasize." (PMID 34975321, 2022). "In the current work, we found an increment of MMP-2 and MMP-9 levels and their potential enzymatic activity in samples from cancer patients." (PMID 36213817, 2022). "In various cancers, aberrant STAT5 signaling increases the expression of target genes, such as cyclin D, Bcl-2, and MMP-2, eventually resulting in the promotion of cell proliferation, survival, and metastasis." (PMID 35563222, 2022). "Among the MMPs, MMP2 and MMP9 are activated upon secretion and are considered to be the most relevant to cancer migration and invasion." (PMID 35223210, 2022). "Previous studies have shown that E-cadherin, N-cadherin, vimentin, MMP2, and MMP9 expression levels can indicate EMT and invasion in various cancers." (PMID 35885009, 2022). "This was explained by the upregulated levels of matrix metalloproteases (MMP-2 and MMP-9) under microgravity, thus playing a crucial role in cancer invasion and migration." (PMID 36613598, 2022). "MMP-9 and MMP-2, stimulated by overexpression of HER2 on cancer cells, degrade type IV collagen and, hence, the vascular basement membrane, enhancing the motility, invasion, and growth of metastatic cells." (PMID 35203510, 2022). "Meanwhile, M2 macrophages can produce various matrix metalloproteinases (MMPs) and chemokines, such as MMP-2, MMP-7, MMP-9, CCL18, and CCL22, which promote the metastasis of cancer cells." (PMID 36685978, 2022). "These 50 drugs were also found to be validated in different cancer cell lines, such as dasatinib, captopril, leflunomide, and dextromethorphan targeting SRC, MMP2, PTK2B, and RAC1 hub genes, respectively." (PMID 35456223, 2022). "RCC tissues that successfully generated organoids highly expressed genes associated with stemness (WNT6/11, FZD8/9 and JAG2), cell matrix (MMP2, COL1A1), fatty metabolism (ACOT2, LIPE) and cancer development (TGFB1, SMAD6/7, EGF and FGF1)." (PMID 35802820, 2022). "MMP2 is a potent activator of TGF-β1, and studies have revealed that MFG-E8 increases the secretion of MMP2 in macrophages and cancer cells." (PMID 35440618, 2022). "Transwell assay results showed that EIF5B silencing decreased the migration of HCC cells by suppressing EMT and decreasing the expression levels of MMP-2 and MMP-9, which are required for cancer progression." (PMID 37305324, 2022). "Members of the MMP family of proteins, particularly MMP2 and MMP9, play a crucial role in cancer metastasis." (PMID 35178352, 2022). "In fact, glucose depletion was found to induce matrix metalloproteinases MMP-2 and MMP-9, suggesting that the increase in cellular proline concentration in cancer cells is a result of collagen degradation." (PMID 35733940, 2022). "MMP2 and MMP9, as the two most important members of the matrix metalloproteinases, play a crucial role in promoting cancer metastasis." (PMID 35783013, 2022). "The repressive result of CA on MMP-2 and MMP-9 is connected with the obstruction of NF-κB activation, as identified in liver tumor cells stimulated via PMA, leading to a reduction in cancer invasiveness and growth." (PMID 35355732, 2022). "NETs enhance the expression of EMT markers ZEB1, Snail and fibronectin, cancer stem cell marker CD44, proinflammatory mediators, such as IL1β, IL6, IL8, CXCR1, MMP2 and MMP9." (PMID 35574410, 2022). "We found that the overexpression of miR-641 expression led to significant decreases in the protein expression levels of Cox-2, MMP-2, and MMP9, which were the crucial indicators of cancer metastasis." (PMID 35069784, 2022).